INS (insulin)
Diseases named in the same sentence as INS in open-access papers (continued):
Sharing a sentence is not in itself a finding about the gene and the disease.
Insulin resistance (continued). "Furthermore, reducing Hsp10 expression in the hypothalamus of C57BL/6N mice causes hypothalamic insulin resistance with acute liver insulin resistance, identifying a novel role for Hsp10 in propagating insulin sensitivity in vivo." (PMID 33946318, 2021). "Therefore, impaired hepatic insulin clearance can be linked to hepatic insulin resistance and hepatic steatosis." (PMID 33972568, 2021). "Conversely, ET-1 may play a causal role in the development of insulin resistance, since it inhibits insulin mediated glucose uptake in adipocytes through ETB receptors." (PMID 34966295, 2021). "The parallel increase in circulating levels of visfatin and insulin could be due to a common association of these parameters with insulin resistance." (PMID 34645898, 2021). "Accumulating studies have demonstrated that the plasma levels of FGF21 increase in parallel with the severity of hepatic steatosis in humans, and are positively associated with TG, fasting insulin, and other insulin resistance indices, while negatively correlated with body mass index and HDL." (PMID 34944728, 2021). "Second, the alteration of brain insulin signaling may be due to insulin resistance associated with induction of cognitive impairments and neurodegeneration." (PMID 33402193, 2021). "However, when these mechanisms fail, an increase in glucose and insulin would be necessary to further increase their transport to skeletal muscle, which can cause insulin resistance." (PMID 34950103, 2021). "Initially, insulin resistance causes β-cellsto secrete more insulin as a way to compensate for the deficiency.Increased metabolic activity of β-cells leads to the formationof reactive oxygen species (ROS) and induction of endoplasmic reticulum(ER) stress that promote inflammation." (PMID 34236862, 2021). "Obese people develop insulin resistance majorly due to augmented inflammatory events in adipocytes through significant modulation in the prime secretory molecules and the key signaling pathways associated with insulin signaling." (PMID 33917607, 2021). "Although glucose uptake in these tissues occurs also through GLUT-1, which provides constitutive insulin-independent glucose uptake, attenuation of downstream insulin signaling at PI3K/AKT in these tissues has been implicated in the development of insulin resistance and T2DM." (PMID 34299331, 2021). "However, postmenopausal women will face reduced insulin sensitivity, increased insulin resistance and a similar risk of T2DM as that of men." (PMID 34307284, 2021). "However, there is some evidence that an effect on hormonal status and HCB pesticides exists, given that higher prepubertal HCB concentrations were associated with greater ratios of insulin resistance, higher serum insulin, and HOMA-IR levels." (PMID 34281107, 2021). "In this study, PG levels at 30 min after MTT might be selected for the risk factor need for insulin therapy though the mechanism of insulin resistance." (PMID 33776619, 2021). "This link could be traced back to insulin, as it recently became apparent that iodine deficiencies and insulin resistance are tightly related." (PMID 33602219, 2021). "In addition to insulin resistance, IL-1 beta has been implicated in impaired insulin secretion and T2D." (PMID 34760952, 2021). "Moreover, low insulin sensitivity, insulin resistance, and type 2 diabetes are risk factors for pancreatic cancer." (PMID 34770068, 2021). "Strikingly, the improvements in whole-body insulin sensitivity were more pronounced in individuals with the lowest baseline insulin sensitivity, underlining the potential of hypoxia exposure as a therapy for people with (severe) insulin resistance." (PMID 33851320, 2021). "This is a significant gap in knowledge since vagal signaling promotes insulin sensitivity in other peripheral organs, and the loss of vagal activity associates with insulin resistance, leading some to conclude that vagal activity is critical to overall insulin sensitivity." (PMID 33776789, 2021).
Insulin resistance (continued). "According to the analysis of the publications and references, it could be found that the study of shared mechanisms between depression and metabolic diseases caused by changes in insulin levels or insulin resistance has attracted widespread attention." (PMID 34366917, 2021). "In the overall patients, multivariate analysis was performed to test whether TYK2PV is independently associated with insulin secretion ability and insulin resistance." (PMID 33799705, 2021). "This complex is highly active in the adipose tissue and in the skeletal muscle of obese mice, causing insulin resistance through inhibition of insulin signaling by the S6K1 pathway, reducing glucose uptake by the muscle, and contributing to systemic insulin resistance." (PMID 34069890, 2021). "Diet-induced obesity is associated with insulin hypersecretion and insulin resistance." (PMID 35011018, 2021). "Hyperinsulinemia caused by decreased insulin clearance may result in secondary insulin resistance via the downregulation of insulin receptors in hepatocytes." (PMID 34948019, 2021). "Phenylalanine, which is positively associated with insulin secretion, may be involved compensation pathways in the early stages of insulin resistance via the stimulation of insulin secretion." (PMID 35069433, 2021). "Additionally, the main cause of this abnormality is insulin resistance (increased levels of insulin at plasma, hyperinsulinemia) and dyslipidemia (hypertriglyceridemia, low HDL cholesterolemia, high LDL cholesterolemia, and abdominal obesity)." (PMID 33673200, 2021). "The loss of pulsatile insulin secretion is an early feature in the development of type 2 diabetes and may be involved in the (patho)genesis of insulin resistance in a variety of circumstances." (PMID 34360563, 2021). "The occurrence and development of insulin resistance is a complex pathological process caused by a decline in insulin sensibility of insulin target organs, subsequent blocking of insulin signaling transduction, and an ultimate decrease in intracellular glucose uptake and utilization." (PMID 35049893, 2021). "A decrease in insulin-induced molecular signaling, termed insulin resistance (IR), is a major pathogenic mechanism in MetS and T2DM, and may contribute to the associated cognitive impairments." (PMID 34512303, 2021). "Obesity can lead to insulin resistance, in turn causing an increase in insulin secretion." (PMID 33693438, 2021). "Therefore, insulin resistance and ultimately loss of insulin secretion results in the dysregulation of platelet activation." (PMID 33946846, 2021). "Meanwhile, a study on PCOS-induced rats reported that treatment with 50, 100 and 200 mg/kg nano curcumin increased the expression of pancreatic PI3K/AKT/mTOR protein levels, which are the pathways reportedly associated with defective insulin level and insulin resistance." (PMID 34579002, 2021). "Surgeons learned, over the years, that type 2 diabetes is a complex heterogeneous disease mainly driven by insulin resistance with a genetic predisposition, inevitably progressive despite glucose-lowering treatment, with 50% of individuals requiring insulin therapy within 10 years." (PMID 33555509, 2021). "TYK2PV is associated with impaired insulin secretion and low insulin resistance in type 2 diabetes." (PMID 33799705, 2021). "The ectopic fat deposition interferes with insulin signaling and causes insulin resistance 11,12." (PMID 33500723, 2021). "The higher concentrations of insulin in Burmese than in MCO cats may indicate insulin resistance and thus be related to the increased risk for DM." (PMID 33886598, 2021). "NWO is associated with insulin resistance, low insulin sensitivity, and high insulin secretion." (PMID 33731778, 2021).
Insulin resistance (continued). "In human skeletal muscle cells, chemerin release was associated with insulin resistance at the level of lipogenesis and insulin-induced antilipolysis in adipocytes owing to activation of p38 MAPK, NF-κB, and extracellular signal-regulated kinase (ERK)-1/2 by chemerin." (PMID 34804428, 2021). "It has been argued that decreased peripheral glucose uptake combined with augmented endogenous glucose production resulting in insulin resistance is associated with the diminished β-cell function and decreased secretion of insulin by the pancreas in type 2 diabetes." (PMID 34575035, 2021). "Moreover, central (or visceral) adiposity is better linked to insulin resistance and plasma levels of glucose, insulin, cholesterol, triglycerides and high-density lipoprotein cholesterol than total adiposity." (PMID 34943836, 2021). "Women with PCOS are often accompanied by insulin resistance, and high levels of insulin may be one of the causes of PCOS." (PMID 33495419, 2021). "Moreover, a higher serum level of C-peptide, a measure of insulin secretion usually elevated in insulin resistance status, has been indicated as a risk factor for colorectal cancer development." (PMID 34205356, 2021). "Insulin resistance has been found to be associated with the development of hypertension, and dietary fiber intake might improve blood pressure by modulating insulin metabolism." (PMID 34604281, 2021). "Previous studies have already demonstrated a correlation between obesity associated adipocyte cell hypertrophy and impaired insulin mediated glucose uptake and increased lipolysis, predicting pathological conditions such as insulin resistance and type 2 diabetes." (PMID 33725017, 2021). "Indeed, insulin resistance is an increasingly relevant risk factor of PD, and administration of insulin has been reported to alleviate cognitive impairment in a 6-OHDA-induced PD model through reducing the levels of p-AKT and p-GSK3β." (PMID 34567221, 2021). "Ceramides have been associated with disrupted insulin signaling and insulin resistance." (PMID 33920193, 2021). "Furthermore, augmented adipose tissue lipolysis was associated with Insulin resistance and impaired insulin secretion, two clinical features determining the development and progression of T2DM." (PMID 33574418, 2021). "Moreover, hyperglycemia, caused by insulin resistance and abnormal insulin secretion, can lead to ROS accumulation and decreased NO bioavailability, thus promoting endothelial dysfunction." (PMID 33708805, 2021). "Insulin resistance and hyperinsulinism alter the systemic and neurohumoral environment, causing changes in metabolism, changes in insulin, signaling in cardiomyocytes developing in the impaired heart, and adverse left ventricular remodeling, contributing to myocardial dysfunction." (PMID 34070103, 2021). "Furthermore, local insulin resistance in the aortic rings caused a significantly reduced insulin-dependent vasorelaxation at higher insulin doses in the VDD groups." (PMID 34502321, 2021). "Ghrelin levels associate with high insulin concentration and insulin resistance." (PMID 34249898, 2021). "Diabetic patients who are not able to secrete insulin are characterized as T1DM, while patients with insulin deficiency or insulin resistance in the human metabolic system, less insulin sensitivity or signaling in the liver, skeletal muscles, and adipose tissue are characterized as T2DM." (PMID 33525758, 2021). "Second, vitamin D and insulin sensitivity: vitamin D insufficiency has been independently associated with metabolic syndrome and insulin resistance, which is the key pathophysiology of NAFLD and supplementation of vitamin D has resulted in improving insulin sensitivity." (PMID 34199258, 2021).
Insulin resistance (continued). "In obese db/db mice (a model of insulin deficiency) higher muscle protein degradation in comparison with control mice (normal plasma insulin concentration) was reported; the authors concluded that insulin resistance was associated with accelerated muscle protein degradation." (PMID 33854837, 2021). "Moreover, in this study, pregnant women with characteristics that favored the development of insulin resistance, such as pre-pregnancy obesity, higher weight gain and need for insulin therapy, were associated with a higher risk of having LGA newborns." (PMID 33939909, 2021). "Foods with added sugar, sweeteners, and/or saturated fats raise blood levels of low-density lipoprotein (LDL), glucose, and insulin, and these level profiles are associated with an increased risk of coronary heart diseases, glucose intolerance, and insulin resistance." (PMID 33921979, 2021). "Moreover, insulin‐associated weight gain can worsen insulin resistance, resulting in the escalation of insulin therapy and, therefore, promote additional weight gain." (PMID 33634589, 2021). "The increase in TG concentration potentially leads to elevation of FFAs, which might decrease insulin sensitivity and consequently cause a vicious circle between elevated TG and insulin resistance." (PMID 34587968, 2021). "Under certain physiological and pathological conditions, cells may become less responsive to insulin and they eventually develop insulin resistance, causing both insulin and serum glucose levels to increase." (PMID 34485137, 2021). "Fasting insulin levels at baseline were increased, and declined in seven out of eight patients during leptin substitution most likely reflecting a reduction in obesity-associated insulin resistance." (PMID 34002033, 2021). "Insulin resistance caused by obesity may exacerbate hyperandrogenism, and hyperandrogenism can increase the resistance to insulin, thus forming a vicious cycle." (PMID 34804936, 2021). "Type 2 diabetes is caused by insufficiencies in insulin secretion and insulin resistance." (PMID 34485124, 2021). "Moreover, similar associations were discovered for fasting insulin and homeostatic model assessment for insulin resistance (HOMA-IR) in PCOS patients in Turkey." (PMID 34563259, 2021). "A growing body of epidemiological evidence has shown that alterations in the insulin-signaling pathway linked with type-2 diabetes (insulin resistance) significantly increase the risk of developing dementia and/or of progression from mild cognitive impairment (MCI) to full blown AD." (PMID 34830036, 2021). "Inactivation of the PI-3K/Akt pathway, a downstream insulin signaling, leads to the loss of insulin signaling in hepatocytes and severe insulin resistance, resulting in uncontrolled glucose production and glycogen synthesis in part through alteration of mRNA expression." (PMID 33800074, 2021). "These other pharmacotherapy options, which are indicated for adults but not for children and adolescents (with the exception of liraglutide), are recommended prior to insulin due to the weight gain associated with insulin, and subsequent increased insulin resistance." (PMID 33634589, 2021). "GDM is mainly caused by insufficient secretion of insulin or insulin resistance, and these reasons are currently considered to be related to genetic and environmental factors, such as high childbearing age, family history, or being overweight or obese, or specific ethnicities, among other factors." (PMID 34886255, 2021). "AA exposure reduces blood insulin levels and causes insulin resistance." (PMID 34831705, 2021). "Furthermore, FMT from lean donors increased insulin sensitivity in patients with the metabolic syndrome and obesity-associated insulin resistance." (PMID 33953692, 2021). "This could result in decreased insulin-stimulated tyrosine phosphorylation and decreased activity of downstream signaling molecules, which in turn causes insulin resistance." (PMID 33868161, 2021).
Insulin resistance (continued). "A similar loss of direct protection of insulin on pancreatic acinar cells, due to insulin resistance, might also explain why type-2 diabetics have an ~3 fold increased risk of developing acute pancreatitis." (PMID 34282152, 2021). "Additionally, our results clearly show the potency of Hsp10 expression in modulating hypothalamic insulin action since a mild reduction was already sufficient to cause insulin resistance." (PMID 33946318, 2021). "Although visceral fat is involved in insulin resistance and impairs cognitive function, subcutaneous fat is associated with lower insulin levels, high testosterone or estrogen levels are associated with higher cognitive function, which brings cognitive advantages to obese people." (PMID 34705855, 2021). "Large-scale clinical studies in the Chinese population have shown that PPARD rs2016520 polymorphism (also named + 294 T > C or − 87 T > C) is associated with blood glucose, insulin level and insulin resistance, and is a key factor affecting the development of metabolic syndrome and T2DM." (PMID 34772419, 2021). "Use of insulin may also increase risk of weight gain, hypoglycemia, metabolic syndrome and CVDs leading to mortality, especially in type 2 DM with insulin resistance." (PMID 34641827, 2021). "Given that insulin resistance and concomitant hyperinsulinemia are associated with renal dysfunction in the general population, the improvement of insulin sensitivity due to alcohol consumption may have a beneficial effect on kidney function." (PMID 33504820, 2021). "Furthermore, apart from the activation of the HPA axis, another major metabolic change caused by trauma is a decrease in the normal metabolism of insulin, which means the occurrence of insulin resistance." (PMID 34772381, 2021). "Thus, insulin resistance in this context appears to depend on impaired insulin signalling caused by exosomal miR‐29s." (PMID 33520119, 2021). "Decreased liver PGC-1α disrupts insulin signaling associated with insulin resistance in NAFLD." (PMID 34439969, 2021). "Moreover, Ruminococcaceae was associated with pregnancy-induced insulin resistance in obese women, and it is possible that the bacteria altered insulin signaling impairment of glucose homeostasis and inflammation." (PMID 34681126, 2021). "Hyperandrogenism can also modulate insulin sensitivity, which may be the key to why insulin resistance was found to be associated with AMH." (PMID 34422047, 2021). "After a standardized protein meal, healthy subjects with relatively higher degree of insulin resistance and glycemia show higher post meal responses of phenylalanine, isoleucine and tyrosine, suggesting that insulin resistance is linked to defective insulin-mediated uptake of these amino acids." (PMID 34717541, 2021). "This clearly suggests the need for extreme caution while preparing food for diabetic individuals to ensure it has not just low GI but also a low insulin index to avoid raising insulin levels in the blood; high insulin concentration is associated with insulin resistance and cardiac risk." (PMID 34395493, 2021). "Thus, we can state that insulin resistance represents both a cause and a consequence of hepatic steatosis, and that fatty acids accumulation in the hepatocytes results in insulin signaling pathway defects in individuals with genetic susceptibility." (PMID 34944682, 2021). "Advanced age could exacerbate the chronic system inflammation and oxidative stress led by PM2.5, and aging is associated with reduced insulin secretion as well as insulin resistance due to the promotion of beta-cell death." (PMID 34484113, 2021). "Administration of testosterone to differentiated, subcutaneous preadipocytes from lean women causes insulin resistance via insulin-stimulated phosphorylation of protein kinase C ζ (PKCζ), which initiates the translocation of glucose into the cell via glucose transporter type 4 (GLUT4)." (PMID 34069293, 2021).